THBD (thrombomodulin)
Diseases named in the same sentence as THBD in open-access papers (continued):
Sharing a sentence is not in itself a finding about the gene and the disease.
cancer (56 papers, 2005 to 2025). A tumor composed of atypical neoplastic, often pleomorphic cells that invade other tissues. "The heightened levels of miR-18a-5p were associated with enhanced cancer cell proliferation, migration, and invasion, alongside a reduction in THBD activity, as demonstrated through CCK-8, Transwell, and dual Luciferase assays." (PMID 40332167, 2025). "Coagulation markers such as D‐dimer, thrombin–antithrombin complex (TAT), and thrombomodulin (TM) show a potential predictive value for cancer‐associated VTE but lack extensive research in NHL." (PMID 39711462, 2024). "The effects of Thrombomodulin activity in cancer have been linked to its roles in anticoagulation, anti-inflammation and tissue adhesion and proliferation." (PMID 33238953, 2020). "Certain evidence implies that changes in the expression or activity of thrombomodulin may be associated with the prothrombotic state often observed in cancer patients, which is related to worse clinical outcomes." (PMID 40332167, 2025). "Beyond its conventional role in blood clotting, THBD has been linked to various cellular processes, including inflammation, cell proliferation, and angiogenesis, all of which are significant in the context of cancer biology." (PMID 40332167, 2025). "The expression of THBD in UCEC demonstrated a statistically significant downregulation when comparing normal tissue to each cancer stage, including stage I, stage II, and stage III (p < 0.05)." (PMID 40332167, 2025). "This investigation revealed that THBD expression is significantly diminished in cancer cells, while miR-18a-5p levels are notably increased when compared to normal endometrial cells." (PMID 40332167, 2025). "Although THBD and miR-18a-5p are inversely related, their roles in cancer biology and survival differ significantly." (PMID 40332167, 2025). "Another mechanism of fibrinolysis suppression in cancer patients includes the dysregulation of the thrombomodulin–thrombin complex that leads to the activation of the thrombin activatable fibrinolysis inhibitor (TAFI) coagulation pathway." (PMID 36010924, 2022). "Four members compose the group XIV of CTLDcps: CD93, Clec14A, CD248, and Thrombomodulin, which have been studied extensively in human and mouse in the contexts of angiogenesis and cancer biology." (PMID 35659564, 2022). "Specifically, the TCGA datasets were integrated to evaluate the correlations of LATS2 expression with the four specific immune cell gene markers (PTPRC, BCL6, NRP1, and THBD) in 33 cancer types." (PMID 34699318, 2021). "Thrombomodulin is a 74 kDa membrane receptor expressed on endothelial cells with important roles in physiological coagulation, inflammation and cancer promotion." (PMID 33238953, 2020). "To investigated the expression of CLEC9A and THBD, and assessed their correlations with overall survival in human cancers, we searched the TCGA database." (PMID 32655564, 2020). "We showed that THBD and C9orf50 harbor low levels of DNA methylation in 15 types of cancer other than CRC, including most high-incidence cancers." (PMID 23209692, 2012). "Obviously, for both GDF15 and THBD, additional studies are necessary to elucidate their role in cancer biology and determine its potential clinical significance." (PMID 15900300, 2005). "Given the heightened risk of metastasis and recurrence associated with the serous subtype, the levels of both miR-18a-5p and THBD could serve as valuable biomarkers for tracking the aggressive progression of cancer." (PMID 40332167, 2025). "In the UCEC cohort we studied, the notably lower THBD gene expression levels in the 61–80 age group compared to the 21–40 and 41–60 age groups may suggest that THBD is a significant biomarker for identifying cancer at younger ages." (PMID 40332167, 2025). "Various clinical factors, including age, cancer stage, comorbidities, and treatment response, significantly influence survival outcomes and may obscure the link between thrombomodulin levels and OS." (PMID 40332167, 2025).
cancer (continued). "Future therapeutic approaches could incorporate miRNA inhibitors or gene therapies that aim to elevate THBD expression, thus providing a targeted strategy to mitigate cancer progression." (PMID 40332167, 2025). "There are also data suggesting that chemotherapy alters serum thrombomodulin levels and confers acquired activated protein C (aPC) resistance, which may play a role in cancer-related VTE in gynecologic cancer patients." (PMID 40332167, 2025). "The group XIV of C-type lectin domain-containing proteins (CTLDcps) is one of the seventeen groups of CTLDcps discovered in mammals and composed by four members: CD93, Clec14A, CD248 and Thrombomodulin, which have shown to be important players in cancer and vascular biology." (PMID 35659564, 2022). "The previous study demonstrated that increased expression of thrombomodulin might reduce the migration of cancer cells by restraining PI3K and Akt." (PMID 34620100, 2021). "Furthermore, LATS2 expression was positively correlated with the expression of PTPRC, BCL6, NRP1, and THBD in almost all cancers in the TCGA database." (PMID 34699318, 2021). "We reanalyzed C-type lectin domain family 9 member A (CLEC9A) and CD141 (THBD) gene expression profiles from the Cancer Genome Atlas (TCGA) database and performed the Kaplan-Meier survival analysis of overall survival for several cancers according to their expression levels." (PMID 32655564, 2020). "Thrombomodulin is considered a protein involved in coagulation, cancer and embryogenesis." (PMID 20051099, 2010). "Inhibiting miR-18a-5p or restoring THBD levels may be crucial in the context of cancer development." (PMID 40332167, 2025). "In addition, low or no expression of thrombomodulin in various cancers has been associated with poor prognosis." (PMID 25364818, 2014). "Furthermore, numerous clinical factors—such as age, cancer stage at diagnosis, comorbidities, treatment strategies, and therapeutic responses—can have a more substantial effect on survival outcomes, potentially obscuring any connection between thrombomodulin levels and overall survival." (PMID 40332167, 2025). "Although the exact mechanisms are not fully understood, earlier studies show that, thrombomodulin maintains cell–cell interactions and also inhibits degradation of the ECM; important factors in cancer proliferation." (PMID 33238953, 2020). "Recently, many epigenetic biomarkers have been studied in cancer diagnosis, including hMLH1, E-cadherin, CDKN2A, CDKN2B and APC in GC and SEPT9, SFRP2, THBD, SDC2, VIM and FBN1 in CRC." (PMID 29137404, 2017). "The primary molecular abnormality in EBV associated LLC of the stomach is global and non-random CpG island methylation in the promoter region of many cancer-related genes (such as LOX, HRASLS, FLNC, HAND1, and THBD)." (PMID 24188515, 2013). "Thrombomodulin is not typically categorized as an oncogene or tumor suppressor gene, in contrast to other genes that are directly involved in cancer progression." (PMID 40332167, 2025). "THBD (also known as thrombomodulin, fetomodulin, and CD141) is not only a thrombin receptor but also an oncodevelopmental antigen, which is considered to modulate cancer cell behaviour related to anticoagulant activity." (PMID 32616892, 2020). "Consistent with this, knockdown of thrombomodulin can compromise the integrity of E‐cadherin‐mediated cell–cell contacts, potentially implicating thrombomodulin downregulation in the induction of EMT in cancer." (PMID 31287944, 2019). "Mesothelial cells are generally positive for calretinin, thrombomodulin, cytokeratin 5/6, WT1, D2-40, vimentin, HBME-1 and CD44H, while polyclonal and monoclonal carcinoembryonic antigen, Ber-EP4, Leu-M1, CA-125, B72.3, PAX8, MOC 31, CA19-9 and ER are the most common markers of carcinoma." (PMID 34068638, 2021).
cancer (continued). "Interestingly, our RNA-Seq data showed that MRPS31P5, MDM4 and THBD were expressed at significantly higher levels only in cancer tissues, while PCNXL3 did not result to be differentially expressed." (PMID 32992457, 2020). "Interestingly, HBME-1, cytokeratin 5/6 and thrombomodulin were differentially expressed in the spheroid in only a few cancer cells, but not in others." (PMID 21305058, 2011).
infection (46 papers, 2007 to 2026). The state of being infected such as from the introduction of a foreign agent such as serum, vaccine, antigenic substance or organism. "We also demonstrated that plasma levels of Serpin E1 (plasminogen activating inhibitor, PAI–1) and thrombomodulin were significantly elevated in the ICU group during first two weeks of the infection implying their association with the severe disease." (PMID 38069327, 2023). "The survival curve was significantly higher in DIC patients with combination therapy than in patients treated with thrombomodulin monotherapy, but this effect was seen only in patients with infection-based DIC." (PMID 36846833, 2023). "These patients due to infection can be the target of combination therapy with antithrombin and thrombomodulin." (PMID 36846833, 2023). "On the other hand, the liver showed a significant decrease in Thbd at 3, 6, and 9 dpi, suggesting a continuous decrease in thrombomodulin production in the liver after the infection." (PMID 34834944, 2021). "A logistic regression analysis was conducted by using age, sex, body weight, initial AT activity, DIC score, platelet count, coadministration of heparin, recombinant thrombomodulin, suspected source of infection, surgery, and supplemented AT dose." (PMID 25220851, 2014). "Thrombomodulin (TM) is involved in a range of host defense mechanisms during infection and plays a pivotal role in activation of protein C (PC) into active protein C (APC)." (PMID 24762740, 2014). "Although treating the primary disease of DIC is the most important point when managing infection-related DIC, the efficacy of anticoagulant drugs for DIC, such as recombinant human soluble thrombomodulin and antithrombin, has been reported." (PMID 34441903, 2021). "For example, TNFSF13B, FOS, POLR3G and PRKCE were down-regulated at 3 h post infection, while ITGB7 and THBD were up-regulated." (PMID 28938587, 2017). "At a median of 37.4 weeks after SARS-CoV-2 infection, participants with prior infection showed higher levels of soluble thrombomodulin (TM) and L-lactate dehydrogenase (LDH) than those without previous infection." (PMID 42129413, 2026). "Neither focus of infection nor presence of shock or emergency surgery before admission influenced syndecan-1, thrombomodulin or protein C quartiles (data not shown)." (PMID 25907781, 2015). "While cluster 7 showed a set of genes involved in cell cycle (P29, APBB2, GPS1) and the TGFβ-pathway (BMPR2, THBD) up-regulated 6 hours post infection, no concise network or significant functions/pathways could be identified." (PMID 18047719, 2007).
cardiovascular diseases (12 papers, 2007 to 2025). "After menopause, estrogen levels decline, which may reduce thrombomodulin levels in older women, eliminating differences between the sexes, but it seems that sTM levels rise during menopause due to the higher risk of cardiovascular diseases, causing ED." (PMID 40332159, 2025). "Changes in plasma biomarkers were related to inflammation and cardiovascular disease, with changes in thrombomodulin (−24%), adiponectin (+68%), sE-selectin (−34%), sICAM-1 (−24%) and proMMP-9 (−31%) levels." (PMID 36829862, 2023). "Kidney 4, which is from a donor with a history of significant cardiovascular disease, had the most severe acute tubular injury, the highest levels of thrombomodulin and IL-6, and the greatest downregulation of miR-126-3p." (PMID 33305131, 2020). "THBD and KLF2 transcripts, associated with ’Cardiovascular disease’ by IPA analysis, were up-modulated in 2 of 3 EGF-stimulated EOC cells." (PMID 23889749, 2013). "We investigated the role of four thrombosis genes: coagulation factor V (F5), intercellular adhesion molecule 1 (ICAM1), protein C (PROC), and thrombomodulin (THBD) in cardiovascular diseases." (PMID 17677000, 2007). "Low concentrations of soluble THBD, especially when present along with elevated soluble ICAM1, predispose to cardiovascular disease (CVD) events." (PMID 17677000, 2007). "Our study explores the role in cardiovascular disease of four thrombosis genes: coagulation factor V, intercellular adhesion molecule 1, protein C, and thrombomodulin." (PMID 17677000, 2007). "Furthermore, calafate consumption was correlated with substantial modulation of plasma biomarkers associated with cardiovascular disease (CVD), encompassing reductions in thrombomodulin (−24%), sE-selectin (−34%), sICAM-1 (−24%), and proMMP-9 (−31%)." (PMID 41300428, 2025). "Proteomic analysis in a subcohort revealed that higher levels of inflammatory and endothelial-related proteins (e.g., IL-18, TNF-R1/2, CSF-1, thrombomodulin, resistin) correlated with higher UPF intake, many of which were prospectively linked to cardiovascular disease." (PMID 41010537, 2025). "Interestingly, two proteins directly linked to cardiovascular diseases (CVD) in in vitro and in vivo studies underwent deregulation: COP9 signalosome complex subunit 9 and thrombomodulin." (PMID 35854198, 2022). "Interestingly, beneficial effects of recombinant thrombomodulin in respiratory, renal, and cardiovascular diseases might depend on its anti-inflammatory mechanisms." (PMID 31416465, 2019). "Plasma samples were used to measure common cardiovascular disease markers (sE-selectin, sICAM-1, Precam-1, sP-selectin, PAI-1 and thrombomodulin)." (PMID 36364913, 2022). "Additionally, we quantified the main inflammatory proteins and cardiovascular diseases, such as IL-6, insulin, leptin, MCP-1, PAI-1 total, resistin, TNF-α, E-selectin, ICAM-1, Pecam-1, P-selectin, proMMP-9, thrombomodulin and adiponectin, in plasma." (PMID 36829862, 2023).
bacterial infections (4 papers, 2021 to 2026). "Recent reports focus on the significance of thrombomodulin (TM), especially the domain 1, lectin-like domain (TM-LeD), which modulates the immune responses to bacterial infections and toxins and various diseases in murine models." (PMID 35277184, 2022).
kidney disease (4 papers, 2017 to 2023). "Thus, thrombomodulin has important cytoprotective effects on the glomerular filtration barrier and a disruption of thrombomodulin signalling may be involved in kidney disease in pre-eclampsia." (PMID 33707524, 2021). "Among serum biomarkers of renal involvement in AAV, the levels of MMP3 and thrombomodulin have been reported to be higher in patients with active renal disease than in those without." (PMID 28962592, 2017).
hematologic malignancy (3 papers, 2015 to 2024). "Patients with hematologic malignancy, however, were in a high thrombomodulin quartile (P = 0.036), and patients with shock at admission were in a higher tPA and PAI-1 quartile (both P <0.01, data not shown)." (PMID 25907781, 2015).
inflammation (3 papers, 2020 to 2024). Aberrant reaction of the microcirculation characterized by movement of fluid and leukocytes from the blood into extravascular tissues. "Studies demonstrating high levels of soluble thrombomodulin in lung inflammation suggest that thrombomodulin release from the cell surface contributes to protein C deficiency." (PMID 39408067, 2024).
peripheral neuropathy (3 papers, 2019 to 2022). A disorder affecting the peripheral nervous system. "Two preclinical studies also found that recombinant thrombomodulin could prevent peripheral neuropathy induced by bortezomib and paclitaxel in rats and mice." (PMID 35359859, 2022). "The purpose of this clinical study was to be the first to explore whether ART-123, a recombinant human soluble thrombomodulin, prevents oxaliplatin-induced peripheral neuropathy (OIPN)." (PMID 32965539, 2020). "Most recently, we have demonstrated that inactivation of macrophage-derived HMGB1 by an anti-HMGB1-neutralizing antibody or a recombinant soluble form of human thrombomodulin (TM), referred to as TMα, completely prevents the development of paclitaxel-induced peripheral neuropathy." (PMID 31666085, 2019).
genetic disorders (2 papers, 2012 to 2023). "In this study, we found that in 45 children diagnosed with aHUS, genetic disorders in complement-regulating genes encoding CFH, CFI, MCP, CFB, C3, and THBD, as well as the presence of αFH with or without a homozygous deletion in CFHR1/3, are linked with clinical presentation, treatment, and outcome." (PMID 22410797, 2012).
benign tumors (1 paper, 2020). "Thrombomodulin mRNA levels were not significantly different between benign tumors and STS." (PMID 33015987, 2020).
vascular disorder (1 paper, 2013). A general term used to describe any disease affecting blood vessels]. "Untargeted recombinant proteins, like activated protein C (APC) and thrombomodulin (TM), have demonstrated beneficial effects in acute vascular disorders, but have failed to have a major impact on clinical care." (PMID 24244621, 2013).
THBD also shares sentences with these, for which no sentence is quoted: lung carcinoma (6 papers); acute myocardial infarction (5); asthma (5); idiopathic pulmonary fibrosis (5); pneumonia (5); liver disease (4); lung adenocarcinoma (4); sarcoidosis (4); adenocarcinoma (3); bleeding disorder (3); endometriosis (3); hemolytic-uremic syndrome (3); influenza (3); thrombophilia (3); abdominal aortic aneurysm (2); acute myeloid leukemia (2); allergies (2); antiphospholipid antibody syndrome (2); arthropathy (2); atrial fibrillation (2); cerebral infarction (2); Crohn disease (2); endotoxemia (2); essential thrombocythemia (2); fibrosis (2); Graves disease (2); head and neck squamous cell carcinoma (2); hemorrhagic fever (2); hepatoma (2); hypereosinophilic syndrome (2).
A further 104 diseases each share a sentence with THBD in 2 papers or fewer.